AVP (arginine vasopressin)
Diseases named in the same sentence as AVP in open-access papers (continued):
Sharing a sentence is not in itself a finding about the gene and the disease.
acute coronary syndrome (2 papers, 2020 to 2024). Signs and symptoms related to acute ischemia of the myocardium secondary to coronary artery disease. "Recently, some data suggests that AVP may contribute to microvascular dysfunction after an acute coronary syndrome supporting this hypothesis." (PMID 38716382, 2024). "Copeptin, a surrogate marker for arginine vasopressin, has shown promising prognostic features in small observational studies and is used clinically for early rule out of acute coronary syndrome." (PMID 32345356, 2020).
Alzheimer disease (2 papers, 2022 to 2024). A progressive, neurodegenerative disease characterized by loss of function and death of nerve cells in several areas of the brain leading to loss of cognitive function such as memory and language. "For instance, in a study using in situ hybridization in human tissues, Swaab and colleagues reported that the amount of AVP mRNA in the hypothalamic suprachiasmatic nucleus of Alzheimer’s disease (AD) patients showed three-fold decrease vs. controls." (PMID 39000096, 2024). "Patients suffering from Alzheimer’s disease have a lower level of AVP in the CSF, and post-mortem studies revealed a reduced expression of AVP immunoreactivity in the hippocampus, nucleus accumbens, and the internal portion of the globus pallidus of AD patients in comparison with controls." (PMID 35207180, 2022).
Arthritis (2 papers, 2020 to 2024). Inflammation of a joint. "We conducted ISH to investigate activation of the HPA axis caused by acute mono-arthritis based on gene expression levels of HPA axis-related peptides including AVP hnRNA and CRH mRNA in the pPVN and POMC mRNA in the AP." (PMID 32117068, 2020). "Therefore, the precise reasons for activation of the OXT/AVP system caused by acute mono-arthritis remains unclear." (PMID 32117068, 2020). "In the present study, we evaluated the effects of acute mono-arthritis on activation of the OXT/AVP system and HPA axis using a carrageenan-induced model of knee arthritis in rats." (PMID 32117068, 2020). "Previous studies including our own used several acute/chronic nociceptive models such as the formalin test and adjuvant arthritis model in rats to examine the effects of acute/chronic nociceptive stimuli on the OXT/AVP system." (PMID 32117068, 2020). "Therefore, we aimed to simultaneously evaluate the effects of acute mono-arthritis on the activity of the OXT/AVP system and the HPA axis." (PMID 32117068, 2020). "Further, AVP, not corticotropin-releasing hormone (CRH), predominantly activates the HPA axis in chronic multiple-arthritis, but the participation of AVP in HPA axis activation in acute mono-arthritis remains unknown." (PMID 32117068, 2020). "In contrast, chronic nociceptive stimuli, such as adjuvant arthritis, downregulate CRH neuronal activity; in these conditions, AVP neurons in the pPVN are more dominant and play crucial roles in HPA axis activation." (PMID 32117068, 2020). "Chronic multiple-arthritis activates the OXT/AVP system, but the effects of acute mono-arthritis on the OXT/AVP system in the same animals has not been simultaneously evaluated." (PMID 32117068, 2020). "In conclusion, the current study demonstrated that acute mono-arthritis activated ipsilateral nociceptive afferent pathways at the spinal level and simultaneously activated both the OXT/AVP system and HPA axis alongside upregulation of relevant gene expression in rats." (PMID 32117068, 2020). "In addition, the HPA axis is activated by both AVP and CRH in acute mono-arthritis with a distinct pattern compared to that in chronic multiple-arthritis." (PMID 32117068, 2020). "Although OXT and AVP may have anti-nociceptive effects on acute mono-arthritis, we did not conduct any pharmacological tests with OXT, AVP, or their antagonists." (PMID 32117068, 2020). "Therefore, in the present study, we decided to assess the effects of (only) arthritis without any systemic factors using the acute mono-arthritis model induced by carrageenan on the activity of OXT/AVP system as well as the HPA axis in the same animals simultaneously." (PMID 32117068, 2020).
atrial fibrillation (2 papers, 2019 to 2025). A disorder characterized by an electrocardiographic finding of a supraventricular arrhythmia characterized by the replacement of consistent P waves by rapid oscillations or fibrillatory waves that vary in size, shape and timing and are accompanied by an irregular ventricular response. "Incidence of new-onset atrial fibrillation was lower in AVP responders than non-responders (4% vs. 14%, p = 0.013)." (PMID 40299108, 2025). "Non-responders developed atrial fibrillation within twelve hours after initiation of AVP treatment more frequently than responders (14% vs. 4%, p = 0.013), which was associated with ICU mortality (OR 3.62, 95%CI 1.05–12.49) in logistic regression." (PMID 40299108, 2025).
autonomic dysfunction (2 papers, 2019 to 2023). "Nocturnal polyuria is multifactorial with fluid retention during the day secondary to autonomic dysfunction, lack of ambulation and arginine vasopressin production disorder." (PMID 36902808, 2023).
cerebral infarction (2 papers, 2020 to 2024). An ischemic condition of the brain, producing a persistent focal neurological deficit in the area of distribution of the cerebral arteries. "AVP is an indicator that reflects the activation of hypothalamic–pituitary–adrenal axis and it was shown to correlate with the state and prognosis of cerebral infarction." (PMID 39777314, 2024). "As a stimulating factor in the HPA-axis, AVP may reflect the degree of stress and aggravate the neuronal damage in patients with cerebral infarction and is positively correlated with the severity of infarction." (PMID 33053113, 2020). "Arginine vasopressin (AVP) is a sensitive indicator that can reflect the activation level of the HPA-axis and correlate with the state and prognosis of cerebral infarction." (PMID 33053113, 2020).
cholestasis (2 papers, 2009 to 2022). Impairment of the bile flow caused by obstruction within the liver, or outside the liver in the bile duct system. "In addition, it has been shown that AVP may modulate hepatocyte tight junctional permeability and thus produce cholestasis." (PMID 19664253, 2009).
Cognitive impairment (2 papers, 2023 to 2025). Abnormal cognition is characterized by deficits in thinking, reasoning, or remembering. "Follow-up 2 months postoperatively confirmed persisting AVP deficiency and cognitive impairment." (PMID 41341140, 2025). "Notably, AVP deficiency has been linked to cognitive impairment in several other case reports." (PMID 41341140, 2025).
drug dependence (2 papers, 2017 to 2018). "AVP in the central nervous system is involved in stress responsivity, drug dependence, and emotional behavior." (PMID 30027498, 2018).
glucosuria (2 papers, 2019 to 2025). "In other words, the findings may not be due to changes in hydration status or AVP per se, but rather represent a response (symptom) to poor glucoregulatory health resulting in glucosuria; AVP then responded to maintain blood volume in response to excessive urinary water losses." (PMID 31141915, 2019).
hemorrhagic stroke (2 papers, 2023 to 2025). A stroke caused by a bleed on the brain. "Recently, studies exploring the detrimental role of AVP in animal models of ischemic and hemorrhagic stroke have supported a positive correlation between copeptin level and stroke severity." (PMID 36768443, 2023). "It is clear that further studies are needed to address differences between ischemic and hemorrhagic stroke regarding AVP-mediated AQP4 expression modulation and edema formation." (PMID 36768443, 2023). "Moreover, the differences between ischemic and hemorrhagic stroke regarding AVP release and the mechanism of action remain largely uncovered." (PMID 36768443, 2023).
Hepatic steatosis (2 papers, 2019 to 2025). Steatosis is a term used to denote lipid accumulation within hepatocytes. "In addition, AVP influences lipid metabolism directly by promoting lipogenesis and suppressing lipolysis, thereby promoting triglyceride accumulation within hepatocytes, a hallmark feature of hepatic steatosis." (PMID 40428796, 2025). "The involvement of AVP in MASLD and hepatic steatosis is multifaced." (PMID 40428796, 2025).
Hyperammonemia (2 papers, 2017 to 2019). An increased concentration of ammonia in the blood. "During fulminant ALF, hyperammonemia leads further increases the level of AVP." (PMID 29216295, 2017).
Hypodipsia (2 papers, 2012 to 2018). Reduced fluid intake (drinking) in a clinical situation where the plasma molarity or sodium concentration normally would induce greater fluid intake. "AVP levels were again in the normal range (3.1 pg/ml) 6 months following self-discontinuation of urea, associated with eunatremia and hypodipsia." (PMID 22325688, 2012). "Isolated hypodipsia with an intact AVP response is a very rare phenomenon." (PMID 30587223, 2018). "Cases of hypodipsia have been described where there appeared to be an intact urinary concentrating ability, but with AVP being secreted in response to the non-osmotic stimulus of hypovolemia." (PMID 30587223, 2018).
insomnia (2 papers, 2023 to 2024). A sleep disorder characterized by difficulty in falling asleep and/or remaining asleep. "AVP has also been implicated in sleep disturbances or insomnia." (PMID 38623339, 2024).
intracerebral hemorrhage (2 papers, 2017 to 2020). A cerebrovascular disorder characterized by bleeding into one or both cerebral hemispheres including the basal ganglia and the cerebral cortex. "AVP has been suggested to play an important role in several brain pathologies that are associated with the formation of brain disorder and edema, including focal cerebral ischemia, intracerebral hemorrhage, and TBI." (PMID 29216295, 2017).
kidney injury (2 papers, 2017 to 2024). Trauma to the kidney. "In summary, our data demonstrate that the perinatal exposure to excessive Na+ intake can induce kidney injury in adult offspring and significantly affect the key mechanisms regulating water balance, fluid intake, and AVP release in response to water deprivation." (PMID 28336818, 2017).
memory impairment (2 papers, 2021 to 2022). "Indeed, in this genetically AVP-deficient rat strain sleep disturbances have already been described and several research groups have already reported memory impairment." (PMID 36555107, 2022). "Furthermore, AVP measurements might help diagnose disorders associated with sleep and memory impairments." (PMID 36555107, 2022). "As our results, HFD- induced precocious puberty mice have memory impairment in adulthood, and TH, NeuN, AVP in hypothalamus related to cognition and memory are significantly reduced." (PMID 34530850, 2021).
metabolic dysfunction-associated steatotic liver disease (2 papers, 2019 to 2025). Metabolic dysfunction-associated steatotic liver disease (MASLD, formerly known as nonalcoholic fatty liver disease or NAFLD) is a type of liver disease that is not caused by alcohol. "We then aimed to expand the scope by examining associations between circulating AVP (and its surrogate marker copeptin) and a range of metabolic disorders, including the relationship between AVP and metabolic dysfunction-associated steatotic liver disease (MASLD) and AVP and cardiovascular health." (PMID 40428796, 2025).
pyelonephritis (2 papers, 2015 to 2020). An inflammatory process affecting the kidney. "Hyperhydration decreases AVP levels and thus may reinforce innate immunity, preventing and limiting pyelonephritis." (PMID 25853137, 2015).
renal hypertension (2 papers, 2021 to 2022). Hypertension caused by the kidney's hormonal response to narrowing or occlusion of the renal arteries. "In renal hypertension, decreased AVP sensitivity and increased NF-κB activity in renal marrow collecting tubes may lead to decreased AQP2 expression." (PMID 35721542, 2022).
renovascular hypertension (2 papers, 2014 to 2015). High blood pressure secondary to renal artery stenosis. "Microinjection of salusin-β into the paraventricular nucleus (PVN) increases BP via the release of norepinephrine and AVP in renovascular hypertensive rats." (PMID 25245503, 2015). "Renovascular hypertension is associated with increases in circulating vasoconstrictors such as AII and AVP, which decrease arteriolar diameter, thereby raising vascular resistance and arterial blood pressure." (PMID 25140254, 2014). "Taken together with the knowledge that blood-borne factors gain ready access to nodose ganglion cell bodies, it is possible that circulating AII and AVP may contribute to the etiology of renovascular hypertension via actions on vagal afferent cell bodies." (PMID 25140254, 2014).
subarachnoid haemorrhage (2 papers, 2023 to 2025). "In the majority of these cases, AVP deficiency occurs following rupture of an ACOM aneurysm and subsequent subarachnoid haemorrhage (SAH)." (PMID 41341140, 2025).
vasculitis (2 papers, 2024 to 2025). "In a rodent model of PE caused by treatment of pregnant rats with arginine vasopressin (AVP), a renal histology including tubular necrosis, narrowing of Bowman’s space, and vasculitis has been reported." (PMID 38473987, 2024).
adenovirus infection (1 paper, 2020). "After validation of the e11 and cy11 strategies—the top performing strategies for detection of AVP activity—a virus-induced cell-based biosensing platform for detection of label-free adenovirus infection was established." (PMID 33374523, 2020). "While comparable sensing strategies were only applied in biochemical or bacterial screening assays, herein we established mammalian cell-based sensors for different cysteine (TEVp and AVP) and aspartic (HIV-1 PR) viral proteases, and a whole cell biosensing platform of adenovirus infection." (PMID 33374523, 2020).
Adrenocortical carcinomas (1 paper, 2013). "Adrenocortical carcinomas seem to have an impaired response to AVP, possibly due to decreased expression of the type V1 receptor." (PMID 24034279, 2013).
airway hyperresponsiveness (1 paper, 2017). "Since airway vagal excitation is reportedly to be associated with the psychological stress-induced/exacerbated airway hyperresponsiveness in asthmatics, arginine vasopressin (AVP) might be involved in stress-related airway vagal excitation." (PMID 28210214, 2017).
alcohol addiction (1 paper, 2025). "Targeting neuropeptides such as CRH and AVP, and their receptors involved in both binge drinking and social behavior, may prevent repeated cycles of binge drinking and hangover from spiraling into alcohol addiction and, ultimately, social isolation." (PMID 41301894, 2025).
alexithymia (1 paper, 2022). An agnosia that is a deficiency in understanding, processing, or describing emotions. "Hormone administration studies could be conducted to investigate the effects of oxytocin and AVP vasopressin on alexithymia-related impairments in stress response, emotion regulation, and social cognition." (PMID 36699481, 2022). "Given these relationships, we think that future investigations into potential effects of AVP on ACTH stress response to CRH in relation to alexithymia could be informative." (PMID 36699481, 2022). "However, to our knowledge, only two studies on AVP included alexithymia as a variable, but reported no analysis results on associations between AVP and alexithymia." (PMID 36699481, 2022).
aseptic meningitis (1 paper, 2021). Inflammation of the membranes surrounding the brain and spinal cord without a bacterial pathogen. "In the patient reported herein with aseptic meningitis, the serum AVP level was relatively low (1.6 pg/mL)." (PMID 34289912, 2021).
asphyxia (1 paper, 2018). A state of general hypoxia and hypercapnia (abnormally elevated carbon dioxide (CO2) levels in the blood), resulting in acidosis, which affects all tissues in the body. "Our results provide important information on the kinetics of AVP/copeptin release during asphyxia, and validate the use of the current rodent model in preclinical work on birth asphyxia." (PMID 29403357, 2018). "The neuroendocrine component of birth asphyxia, in particular the increase in circulating levels of arginine vasopressin (AVP), has been extensively studied in humans." (PMID 29403357, 2018).
behavioral disorders (1 paper, 2015). "Because it is impossible to directly manipulate AVP or its receptors within specific brain areas in humans, the relationship between AVP and behavioral disorders has been assessed by correlating plasma AVP levels or V1a receptor promoter polymorphisms with behaviors associated with these disorders." (PMID 25705203, 2015).
Bradycardia (1 paper, 2008). A slower than normal heart rate (in adults, slower than 60 beats per minute). "This was an effect of the induced bradycardia since HR simultaneously dropped from 114 ± 6 beats/min to 88 ± 6 beats/min (p = 0.004) whereas stroke volume remained unaffected (22 ± 2 ml IR versus 19 ± 2 ml AVP-initial, not significant)." (PMID 18291025, 2008).
cerebral (1 paper, 2024). "This suggests that a large infarct may likely result in a greater consequent cerebral oedema and hence, a higher AVP release." (PMID 38957516, 2024).
colon diseases (1 paper, 2022). "The obtained results suggest that the AVP-dependent AQP3 pathway might represent a possible target in colon diseases associated with abnormal cell growth." (PMID 35874817, 2022). "Nevertheless, the obtained data suggest that the AVP-dependent AQP3 pathway might represent a novel target in colon diseases associated with abnormal cell growth." (PMID 35874817, 2022). "Overall, data suggest that dDAVP, through the V1aR dependent pathway, reduces AQP3 mediated glycerol uptake, a process that is reversed in adenocarcinoma, suggesting that the AVP-dependent AQP3 pathway may represent a novel target in colon diseases associated with abnormal cell growth." (PMID 35874817, 2022).
colorectal cancer (1 paper, 2017). A primary or metastatic malignant neoplasm that affects the colon or rectum. "Desmopressin (dDAVP) is a synthetic analog of AVP that acts as a selective agonist for the V2r, which shows antitumor properties in breast and colorectal cancer models." (PMID 28194370, 2017). "Interestingly, there is evidence of the expression of AVP and their receptors in SCLC, breast, pancreatic and colorectal cancer, and human gastrointestinal tumors." (PMID 28194370, 2017).
dementia (1 paper, 2020). Loss of intellectual abilities interfering with an individual's social and occupational functions. "Finally, one other group reported reduced levels of AVP mRNA in the SCN but they did not count AVP mRNA-expressing neurons, and the same group had previously reported no change in AVP-expressing SCN neurons in elderly dementia patients compared to healthy age-matched controls." (PMID 33013301, 2020).
distal renal tubular acidosis (1 paper, 2024). A kidney disorder of impaired net acid secretion by the distal tubule characterized by hyperchloremic metabolic acidosis. "Side effects of AmB that have been observed include nephrotoxicity (distal renal tubular acidosis, arginine vasopressin resistance), electrolyte abnormalities (renal potassium sparing), fever with rigors at the beginning of infusion, and rarely malaise, rash, and bone marrow suppression." (PMID 38673673, 2024).
Dysmenorrhea (1 paper, 2023). Pain during menstruation that interferes with daily activities. "In this context, the research efforts on an arginine-vasopressin (AVP) related approach for treatment of dysmenorrhea are worth mentioning." (PMID 38130407, 2023).
emotional dysregulation (1 paper, 2021). "This highlights the interaction of arginine vasopressin-dependent signaling with the 5-HT system in the brainstem following MS as a potential therapeutic target for treating emotional dysregulation." (PMID 33686115, 2021).